RNU6-173P (RNA, U6 small nuclear 173, pseudogene)
Gene: Small nuclear RNA gene on chromosome 4 (188,121,531 to 188,121,634, reverse strand). Ensembl gene ENSG00000201085.
Homologues: Orthologues: chimpanzee U6 (95% identical), macaque U6 (88% identical), dog U6 (81% identical), rabbit U6 (78% identical). Paralogues in human: RNU6-12P (88% identical), RNU6-13P (88% identical), RNU6-32P (88% identical), RNU6-33P (88% identical), RNU6-41P (88% identical), RNU6-1 (88% identical), RNU6-1060P (88% identical), RNU6-116P (88% identical), RNU6-125P (88% identical), RNU6-15P (88% identical), RNU6-17P (88% identical), RNU6-18P (88% identical), and 1285 more.